RN7SKP208 (RN7SK pseudogene 208)
Gene: Miscellaneous RNA gene on chromosome 2 (55,951,654 to 55,952,014, reverse strand). Ensembl gene ENSG00000202344.
Homologues: Orthologues: chimpanzee 7SK (86% identical). Paralogues in human: RN7SKP124 (65% identical), RN7SKP90 (65% identical), RN7SKP249 (64% identical), RN7SKP255 (64% identical), RN7SKP165 (64% identical), 7SK (63% identical), RN7SKP6 (63% identical), RN7SKP203 (63% identical), RN7SKP3 (63% identical), RN7SKP71 (63% identical), RN7SKP162 (63% identical), RN7SKP127 (63% identical), and 283 more.